RN7SKP125 (RN7SK pseudogene 125)
Gene: Miscellaneous RNA gene on chromosome 9 (117,276,985 to 117,277,286, forward strand). Ensembl gene ENSG00000222413.
Homologues: Orthologues: chimpanzee 7SK (98% identical), guinea pig 7SK (61% identical), guinea pig 7SK (59% identical), mouse Gm56071 (57% identical). Paralogues in human: RN7SKP180 (74% identical), RN7SKP79 (73% identical), RN7SKP9 (73% identical), 7SK (73% identical), RN7SKP243 (73% identical), RN7SKP71 (73% identical), RN7SKP25 (72% identical), RN7SKP173 (72% identical), RN7SKP203 (72% identical), RN7SKP217 (72% identical), RN7SKP255 (72% identical), RN7SKP44 (72% identical), and 284 more.